MALAT1 (metastasis associated lung adenocarcinoma transcript 1)
Diseases named in the same sentence as MALAT1 in open-access papers (continued):
Sharing a sentence is not in itself a finding about the gene and the disease.
cancer (continued). "This might account for the significantly inverse miR663a–MALAT1 relationship observed in CC tissues containing a high proportion of proliferating cancer cells but not in an equal number of SM samples containing a few proliferating tissue stem cells." (PMID 30154407, 2018). "Although Malat1 is not essential in living mice maintained under normal breeding conditions, MALAT1 has an important role in the study of human cancer: MALAT1 is overexpressed in many solid tumors." (PMID 29632545, 2017). "These tumorigenic properties of MALAT1 were mediated by its ability to decoy miR-1 and, consequently, increase the expression of miR-1 target, SNAI2 (snail family transcriptional repressor 2), also named Slug, an oncogene involved in regulation of cancer cell invasion." (PMID 29147648, 2017). "This further confirms our hypothesis that the functional effect of MALAT1 on tumor progression and metastasis is context dependent upon the molecular subtype and clinical phenotype of the cancer, and not merely based upon its expression level alone." (PMID 27250026, 2016). "What is more, MALAT-1 was also over-expressed in other types of cancer.MALAT-1 may serve as an oncogenic long noncoding RNA in PC by promoting EMT and increasing the expression of cancer stem cell markers." (PMID 27429196, 2016). "The prognostic role of MALAT1 in each type of cancer could not be evaluated because of the limited data available." (PMID 26420912, 2015). "However, many lncRNAs have been found to be differentially expressed in a variety of cancers and may act as either oncogenes, such as MALAT-1, HOTAIR, and ANRIL, or tumor suppressor genes, such as MEG3, lincRNA-p21, and PTENP1, in cancer development." (PMID 24036441, 2013). "Therefore, both HOTAIR and MALAT1, as well as probably other lncRNAs, may serve as a crucial linker between autophagy and EMT, orchestrating complex regulatory networks that facilitate cancer progression and resistance to therapy." (PMID 39716252, 2024). "Treatment of cancer cells derived from TBNC with high concentration of 17β‐estradiol (E2) induce reduction in MALAT1 mRNA expression by post‐transcriptional degradation, which indicates targeting the expression of MALAT1 in TNBC could be useful option for therapy development." (PMID 37795578, 2023). "We found lots of them might play a key role in the transformation of enterocyte progenitor cells to cancer cells such as MALAT1, B2M, EEF1A1, RPL5, B3GNT7, RHOB and ACTB might play a key role in the transformation of enterocyte progenitor cells to cancer cells." (PMID 36944972, 2023). "In addition, miR-204-5p serves as a cancer suppressor gene by modulating oncogenic Wnt/FZD signaling pathways, inhibiting NUAK family kinase 1 (NUAK1) in NSCLC, and mediating a long-noncoding RNA (lncRNA) MALAT1 effect on the epithelial-to-mesenchymal transition (EMT) and cells invasion." (PMID 32102656, 2020). "MALAT1 is one of the most established and conserved long non-coding RNAs frequently found in exosomes of human cells and plays a role in regulating cellular proliferation and angiogenesis, and has been proposed as a biomarker for the diagnosis of cancer metastasis." (PMID 29371689, 2018). "Therefore, it has been suggested that MALAT1 overexpression in cancer may drive gain-of-function phenotypes not observed during normal tissue development or homeostasis." (PMID 29641489, 2018). "In supporting with the previous findings, the current analysis found that plasma-based MALAT-1 testing presented a better AUC value than the serum-, tissue- and urine-based analyses, indicating that plasma might be a suitable matrix for the analysis of MALAT-1 expression in cancers." (PMID 29254244, 2017). "Regardless of stage, MALAT1, NEAT1, CRNDE, and FENDRR consistently exhibited the highest degrees, indicating their widespread and stable regulatory roles in cancer progression." (PMID 40728857, 2025).
cancer (continued). "The synergy between MALAT1 and ALKBH5 was consistently observed in stage four across four cancers but exhibited negative correlations in KIRP and SKCM, while showing positive correlations in STAD and THCA." (PMID 40728857, 2025). "XIST, MALAT1, NEAT1, and LINC00240 up-regulated lncRNA were predicted to bind to hsa-mir-124-3p and promoted the proliferation and metastasis of other cancers by modulating hsa-mir-124-3p, but there are no related studies in CCRCC." (PMID 36531222, 2022). "MALAT1 rs3200401 and PVT1 rs13255292 SNPs were assessed with different types of cancer, but not yet extensively investigated in CRC." (PMID 34200314, 2021). "Based on higher co-expression in malignant (n = 11) but not in benign (n = 8) nodules after surgery, MALAT1, PVT1 and HOTAIR were selected as putative cancer biomarkers to analyze 135 FNA samples." (PMID 33030666, 2021). "Like MALAT1, STAT3 dysregulation is not unique to ES due to its many roles in proliferation, migration, angiogenesis and microenvironment conditions in a variety cancers, and it is a popular target for a multitude of pharmaceutical inhibitors." (PMID 34440137, 2021). "To investigate endogenous expression levels of MALAT1, we first determined the expression of MALAT1 in several breast cell lines, including MCF-10A (non-cancerous mammary gland epithelial cell), MCF-7 (luminal A cancer), and MDA-MB-231 (triple negative cancer)." (PMID 34012919, 2021). "Similarly, MALAT1 and NEAT1, other commonly-studied lncRNAs frequently reported to act as miRNA sponges in cancer, are similarly not enriched in number of binding sites." (PMID 31419261, 2019).
tumor (980 papers, 2007 to 2026). "MALAT1 regulates the expression of genes associated with tumor metastasis by recruiting chromatin modification complexes and altering the structure and accessibility of chromatin." (PMID 41394878, 2025). "One of the most studied oncogenic lncRNAs in DLBCL is Metastasis-Associated Lung Adenocarcinoma Transcript 1 (MALAT1), which plays a key role in modulating tumor-associated macrophages (TAMs)." (PMID 40299416, 2025). "MALAT1 exhibits distinct expression across various tumors, and elevated MALAT1 expression is linked to poor tumor prognosis." (PMID 40597438, 2025). "Metastasis-associated lung adenocarcinoma transcript 1 (MALAT1) is a lncRNA that is abundantly expressed in the nucleus and up-regulated in neoplastic diseases." (PMID 39904996, 2025). "This association underscores the role of MALAT1 in driving tumor invasiveness and metastatic spread." (PMID 40674376, 2025). "This study aims to quantify SOX2, PIWI proteins, and MALAT1 in plasma samples and evaluate their correlation with IHC-based tumor markers to assess their diagnostic potential." (PMID 40674376, 2025). "Stable and specific in biofluids, noncoding RNAs such as oncogenic miR‐21, tumor‐suppressive miR‐34a, and metastasis‐associated MALAT1/HOTAIR further enhance clinical applicability." (PMID 40959208, 2025). "MALAT1: A highly conserved lncRNA, MALAT1 is implicated in tumour progression through its ability to regulate cell proliferation, migration and epithelial‐to‐mesenchymal transition (EMT)." (PMID 41261348, 2025). "MALAT1, is associated with poor prognosis in breast cancer patients and promotes tumour cell migration and invasion." (PMID 39912983, 2025). "For example, the lncRNA metastasis-associated lung adenocarcinoma transcript 1 (MALAT1) overexpression induces reprogramming of the tumor microenvironment in LUAD to drive metastasis." (PMID 40149594, 2025). "MALAT1 was established to be upregulated in various tumor tissues, and the overexpression of MALAT1 was associated with adverse clinical features." (PMID 38892191, 2024). "LncRNA MALAT1 (Metastasis-Associated Lung Adenocarcinoma Transcript 1) can sequester miR-204, leading to increased expression of oncogenic mRNAs and promoting tumor growth and metastasis in HCC." (PMID 39211780, 2024). "We further validated the levels of MALAT1 and of other tumor-associated lncRNAs using digital droplet PCR." (PMID 39596626, 2024). "High expression of MALAT1 was detected in healthy tissues, which indicates a potential risk of tumor occurrence and infiltration." (PMID 39764614, 2024). "The investigation has shown that tumor tissues and tumor-associated macrophages (TAMs) exhibit higher quantities of MALAT-1 and fibroblast growth factor 2 (FGF-2) than normal tissue." (PMID 38511067, 2024). "High expression of MALAT1 in diverse tumor types is consistently associated with poor patient survival outcomes." (PMID 39196297, 2024). "The presence of lymph node metastases in these individuals is linked to elevated levels of MALAT1 expression, which is also connected with higher grades of histological evaluation and the stage of the tumor." (PMID 39512820, 2024). "High MALAT1 expression has been significantly linked to an increased risk of tumor recurrence after surgical resection." (PMID 39471147, 2024). "The LCM-RNAseq highlighted, among the thirty common most expressed genes, a well-characterized tumor-associated lncRNA, MALAT1." (PMID 39596626, 2024). "MALAT1 was discovered because its high expression was associated with tumor metastasis and patients’ poorer survival in early-stage non-small-cell lung cancer." (PMID 39768127, 2024).
tumor (continued). "According to reports, elevated MALAT1 expression is associated with a poor prognosis, tumor development, metastasis, chemoresistance, and tumor radioresistance." (PMID 38517388, 2024). "Lower expression mRNA levels of MALAT1 were associated with pathologic stage and lymph node metastasis and tumor T status in all LADC or EGFR wild-type." (PMID 38517388, 2024). "Currently, a study demonstrated that exosome lncRNA MALAT1 secreted by tumor cells was upregulated in the serum of patients with OC and that high serum exosome MALAT1 levels were associated with poor outcome in clinical patients." (PMID 38725621, 2024). "In particular, patients with OSCC who carried the MALAT1 rs619586 polymorphism showed significant differences in both clinical stage and tumor size." (PMID 39408657, 2024). "As a lncRNA, the metastasis-associated lung adenocarcinoma transcript 1 (MALAT1) is oncogenic in numerous tumours progressions." (PMID 37284313, 2023). "Given the key roles mediated by MMP2 and MMP9 in tumor metastasis, their association with MALAT1 and ALKBH5 was subsequently investigated." (PMID 37639643, 2023). "As for its implications in OC pathways, MALAT1 is usually upregulated, which is associated with advanced disease stages, high tumour burden and a poor prognosis." (PMID 38203310, 2023). "The knockdown of MALAT1 by specific ASOs in breast and lung cancer mouse models caused slower tumor growth and a decrease in metastasis." (PMID 37047365, 2023). "For example, up-regulation of MALAT1 has been shown to be associated with tumor invasion and metastasis in colorectal cancer, prostate cancer, and lung cancer." (PMID 37653482, 2023). "For example, one research has shown that metastasis-associated lung adenocarcinoma transcript 1 (MALAT1) can promote tumor cell invasion and migration, whose expression level was elevated in patients with bone metastasis." (PMID 37404755, 2023). "High MALAT-1 expression has been associated with advanced tumor stage, metastasis, and reduced overall survival." (PMID 38124072, 2023). "Abnormal expression of MALAT1 in ovarian cancer is associated with tumor invasion and poor prognosis." (PMID 37653482, 2023). "Metastasis-associated lung adenocarcinoma transcript 1 (MALAT1) is usually overexpressed in deteriorated neoplasms, including NSCLC." (PMID 36979715, 2023). "A recent study showed that MALAT1 upregulation was significantly associated with increased tumor progression and metastases in patients with OS." (PMID 36831169, 2023). "MALAT1 (metastasis-associated lung adenocarcinoma transcript 1) is an extensively investigated lncRNA, especially in tumour biology." (PMID 36817434, 2023). "MALAT1, as a sponge for miR-125a, regulates IL-21R signaling, participates in immune regulation of immune cells and tumor progression, and is a risk factor for survival and recurrence in GC." (PMID 35794986, 2022). "For example, the lncRNA Malat1 has been implicated in both oncogenesis and tumor suppression when examining gene expression profiles in human tumors and in vitro mechanistic studies." (PMID 35681513, 2022). "Metastasis-associated lung adenocarcinoma transcript 1 (MALAT1) is often regarded as a tumor-related lncRNA, and recent papers have reported its potential function in MSC differentiation." (PMID 36581789, 2022). "Several lncRNAs, including TNRC6C-AS, AFAP1-AS1, GAS8-AS1, NONHSAT129183, and MALAT1, were found to be associated with tumor progression in TC." (PMID 35265169, 2022). "The results showed slower tumor growth accompanied by significant differentiation into cystic tumors and a reduction in metastasis upon loss of MALAT1." (PMID 36387279, 2022). "MALAT1 expression was linked to invasion, tumor stage, poor survival, tumor size and metastasis in PDAC patients." (PMID 36212476, 2022). "Further in vivo experiments have shown that, inside target cells, MALAT1 caused increased cell proliferation, promoting tumor growth." (PMID 36012109, 2022).
tumor (continued). "One such lncRNA, named MALAT1, is frequently enhanced in tumors and metastases, while its overexpression is positively associated with tumor progression and metastasis in numerous cancers, including BC." (PMID 35813865, 2022). "Take several well-known lncRNAs in HCC as examples, metastasis-associated lung adenocarcinoma transcript 1 (MALAT1) was investigated to promote tumor metastasis and resistance to 5-FU, DOX, and mitomycin." (PMID 34980201, 2022). "The MALAT1 loss results in slower tumor growth by inducing alterations in the gene expression and changes in the splicing patterns of the genes involved in differentiation and protumorigenic signaling pathways." (PMID 36012617, 2022). "Patients with high MALAT1 expression had a significantly increased risk of tumor recurrence after liver transplantation, pointing MALAT1 as an independent prognostic factor." (PMID 33477833, 2021). "Compared to the overall OSCC group, development of advance clinical (III+IV) and tumor T stage (>T2) was further strengthened in the betel quid-chewing subgroup who harbored at least one polymorphic G allele of MALAT1 rs619586." (PMID 34268119, 2021). "Previous studies show that metastasis associated lung adenocarcinoma transcript 1 (MALAT1) is related to the occurrence, development, metastasis, and prognosis of multiple tumor types, including OS." (PMID 34373692, 2021). "For instance, the binding site for miR-217, which is associated with tumor suppression, is subject to linearization in K562 cells, which would allow MALAT1 to sponge miR-217." (PMID 33450947, 2021). "Emerging evidence demonstrated that the dysregulation of MALAT1 was implicated in tumor progression." (PMID 34222668, 2021). "We observed that OSCC patients with the smoking or drinking habit who had at least one G allele of MALAT1 rs619586 were at higher risk of developing advance clinical stage and larger tumor sizes compared to those patients with AA homozygotes." (PMID 34268119, 2021). "NEAT1 and MALAT1 are well characterized lncRNAs and have been implicated in tumor progression, including GBM." (PMID 33466745, 2021). "In these studies, several lncRNAs, including MEG3, Linc0152 and MALAT1, were identified to play a critical role in the regulation of tumor angiogenesis in IH and demonstrated to be associated with the development of IH." (PMID 33430906, 2021). "The latest studies report that MALAT1 expressed by tumor associated DCs is attributable to the epithelial-to-mesenchymal transition (EMT), invasion, and migration of tumor cells in colon cancer." (PMID 34900986, 2021). "So, we also studied the association of MALAT1 level with immune cell infiltrating in tumor with TIMER website." (PMID 34308750, 2021). "MALAT1 promotes the proliferation and invasion of tumor cells, affects the drug resistance of tumor cells, and is associated with the poor prognosis of a variety of solid tumors." (PMID 34761116, 2021). "In thyroid tumors, MALAT1 promotes Fibroblast Growth Factor 2 (FGF2) secretion from tumor-associated macrophages into the tumor microenvironment to mediate angiogenesis." (PMID 34512715, 2021). "Third, the MALAT1/miR-124 axis regulates cervical cell proliferation, at least in part, associated with the development of tumor growth and survival rates." (PMID 34221014, 2021). "Overexpression of lncRNA MALAT1 partially suppressed H2 caused inhibition of tumor growth whereas miR-124-3p counteracted the effect of lncR MALAT1." (PMID 33482814, 2021). "Another crucial lncRNA is MALAT-1 (metastasis-associated lung adenocarcinoma transcript-1), which is aberrantly upregulated in multiple tumor types, and yields high proliferative and metastatic profiles." (PMID 34198989, 2021). "EVs play a role in tumor angiogenesis as they have been shown to transfer metastasis-associated lung adenocarcinoma transcript 1 (MALAT1) from epithelial OC to human umbilical vein endothelial cells (HUVECs), resulting in promoting HUVECs angiogenesis." (PMID 34203051, 2021).